TRPV4 (transient receptor potential cation channel subfamily V member 4)
Description:
Non-selective calcium permeant cation channel involved in osmotic sensitivity and mechanosensitivity. Activation by exposure to hypotonicity within the physiological range exhibits an outward rectification. Also activated by heat, low pH, citrate and phorbol esters. Increase of intracellular Ca(2+) potentiates currents. Channel activity seems to be regulated by a calmodulin-dependent mechanism with a negative feedback mechanism. Promotes cell-cell junction formation in skin keratinocytes and plays an important role in the formation and/or maintenance of functional intercellular barriers (By similarity). Acts as a regulator of intracellular Ca(2+) in synoviocytes. Plays an obligatory role as a molecular component in the nonselective cation channel activation induced by 4-alpha-phorbol 12,13-didecanoate and hypotonic stimulation in synoviocytes and also regulates production of IL-8. Together with PKD2, forms mechano- and thermosensitive channels in cilium. Negatively regulates expression of PPARGC1A, UCP1, oxidative metabolism and respiration in adipocytes (By similarity). Regulates expression of chemokines and cytokines related to pro-inflammatory pathway in adipocytes (By similarity). Together with AQP5, controls regulatory volume decrease in salivary epithelial cells (By similarity). Required for normal development and maintenance of bone and cartilage. In its inactive state, may sequester DDX3X at the plasma membrane. When activated, the interaction between both proteins is affected and DDX3X relocalizes to the nucleus. In neurons of the central nervous system, could play a role in triggering voluntary water intake in response to increased sodium concentration in body fluid (By similarity). [Isoform 1]: Non-selective calcium permeant cation channel involved in osmotic sensitivity and mechanosensitivity. Activation by exposure to hypotonicity within the physiological range exhibits an outward rectification. Also activated by phorbol esters. Has the same channel activity as isoform 1, and is activated by the same stimuli. [Isoform 5]: Non-selective calcium permeant cation channel involved in osmotic sensitivity and mechanosensitivity. Activation by exposure to hypotonicity within the physiological range exhibits an outward rectification. Also activated by phorbol esters. Has the same channel activity as isoform 1, and is activated by the same stimuli. [Isoform 2]: Lacks channel activity, due to impaired oligomerization and intracellular retention. [Isoform 4]: Lacks channel activity, due to impaired oligomerization and intracellular retention. [Isoform 6]: Lacks channel activity, due to impaired oligomerization and intracellular retention. (Microbial infection) Facilitates hepatitis C virus (HCV) replication, possibly through its action on DDX3X. (Microbial infection) Facilitates Dengue virus (DENV) replication, possibly through its action on DDX3X. (Microbial infection) Facilitates Zika virus (ZIKV) replication, possibly through its action on DDX3X.
Synonyms: OTRPC4; TRP12; VRL-2; VR-OAC; VRL2; VROAC; CMT2C; BCYM3; HMSN2C; SMAL; SPSMA; SSQTL1
Tractability: Small molecule: an approved drug acts on it; a structure with a bound ligand is known; a high-quality ligand is known; it belongs to a druggable protein family. Antibody: UniProt places it where antibodies can reach, with high confidence; its Gene Ontology location is reachable by antibodies, with high confidence; UniProt predicts a signal peptide or a membrane-spanning region. PROTAC: ubiquitination databases record sites on it; a small molecule that binds it is known.
Target class: Voltage-gated ion channel; Ion channel; Transient receptor potential channel
Chemical probes: GSK1016790A (high quality)
Gene: Protein-coding gene on chromosome 12 (109,783,087 to 109,833,406, reverse strand). Ensembl gene ENSG00000111199.
Subcellular location: Cell membrane; Apical cell membrane; Cell junction, adherens junction; Cell projection, cilium; Cell membrane (Isoform 1); Cell membrane (Isoform 5); Endoplasmic reticulum (Isoform 2); Endoplasmic reticulum (Isoform 4); Endoplasmic reticulum (Isoform 6)
Pathways (Reactome):
Cellular responses to stimuli: High laminar flow shear stress activates signaling by PIEZO1 and PECAM1:CDH5:KDR in endothelial cells
Transport of small molecules: TRP channels
Gene Ontology:
Molecular function: calcium channel activity; calmodulin binding; identical protein binding; monoatomic cation channel activity; protein binding; protein kinase binding; stretch-activated, monoatomic cation-selective, calcium channel activity; actin binding; actin filament binding; alpha-tubulin binding; beta-tubulin binding; microtubule binding; protein kinase C binding; SH2 domain binding; monoatomic ion channel activity; osmosensor activity
Biological process: blood vessel endothelial cell delamination; calcium ion import into cytosol; calcium ion transmembrane transport; calcium ion transport; cartilage development involved in endochondral bone morphogenesis; cellular hypotonic response; intracellular calcium ion homeostasis; multicellular organismal-level water homeostasis; positive regulation of cytosolic calcium ion concentration; positive regulation of vascular permeability; actin cytoskeleton organization; actin filament organization; calcium ion import; calcium ion import across plasma membrane; cell volume homeostasis; cell-cell junction assembly; cellular response to heat; cellular response to osmotic stress; cortical microtubule organization; microtubule polymerization; negative regulation of neuron projection development; osmosensory signaling pathway; positive regulation of microtubule depolymerization; response to mechanical stimulus; cellular hypotonic salinity response; and 22 more
Cellular component: apical plasma membrane; endoplasmic reticulum; plasma membrane; adherens junction; cilium; cortical actin cytoskeleton; cytoplasmic microtubule; filopodium; focal adhesion; growth cone; lamellipodium; membrane; ruffle membrane; cell surface
Genetic constraint (gnomAD): Loss-of-function variants: 58 observed, 87.63 expected, observed/expected ratio (o/e) 0.66, 90% interval 0.54 to 0.82. The upper end of that interval is the gene's LOEUF score, 0.82, which puts it in group 3 of 6, group 1 being the genes least tolerant of losing a copy. Missense variants: 879 observed, 1,220.8 expected, observed/expected ratio (o/e) 0.72, 90% interval 0.68 to 0.76. Synonymous variants: 489 observed, 519.52 expected, observed/expected ratio (o/e) 0.94, 90% interval 0.87 to 1.01.
Gene-disease validity (ClinGen):
ClinGen rates the evidence that TRPV4 causes each of these diseases.
neuromuscular disease (autosomal dominant): Definitive.
TRPV4-related bone disorder (autosomal dominant): Definitive.
Homologues: Orthologues: chimpanzee TRPV4 (99% identical), macaque TRPV4 (99% identical), pig TRPV4 (97% identical), guinea pig TRPV4 (95% identical), mouse Trpv4 (95% identical), rat Trpv4 (95% identical), dog TRPV4 (91% identical), tropical clawed frog trpv4 (77% identical), rabbit TRPV4 (74% identical), zebrafish trpv4 (69% identical), tropical clawed frog trpv4l.1 (59% identical), Caenorhabditis elegans ocr-4 (21% identical), and 3 more. Paralogues in human: TRPV1 (42% identical), TRPV2 (37% identical), TRPV3 (35% identical), TRPV5 (24% identical), TRPV6 (23% identical).
Diseases named in the same sentence as TRPV4 in open-access papers:
TRPV4 is named in the same sentence as 365 diseases in open-access papers, as found by Europe PMC text mining. Sharing a sentence is not in itself a finding about the gene and the disease. The quoted sentences say what the papers report.
breast carcinoma (49 papers, 2016 to 2025). "The expression of TRPV4 in human clinical samples, as observed in public databases, demonstrates an upregulation specifically in the underlying subtype of breast cancer." (PMID 40078961, 2025). "Analyses of patient-derived breast cancer tissues confirmed that plasma membrane-associated TRPV4 is specific to high-grade DCIS and indicates the presence of a pro-invasive cell volume reduction mechanotransduction pathway." (PMID 40256993, 2025). "High TRPV4 protein levels are linked to basal-like breast cancer subtypes and its abnormal expression has also been found in the metastatic sites of invasive ductal carcinomas, linking TRPV4 to the mechanisms behind invasive potential." (PMID 38514727, 2024). "The functional significance of high TRPV4 expression in breast cancers has been mainly linked to migration and spread of cancer cells." (PMID 38514727, 2024). "An abnormal TRPV4 expression is linked to gastric, liver, pancreatic, colorectal, lung, and breast cancers." (PMID 37892239, 2023). "Abnormal TRPV4 expression is linked to at least gastric, liver, pancreatic, colorectal, lung and breast cancers." (PMID 34356643, 2021). "We have previously demonstrated that TRPV4 expression is also associated with a breast cancer gene cluster (referred to as Red Module) that is strongly associated with EGFR, a gene often involved in the EMT process." (PMID 33322037, 2020). "As such, TRPV4 mRNA expression has been linked to a diminished distant metastasis free-survival in breast cancer samples." (PMID 31275168, 2019). "In contrast, loss of TRPV4 expression inhibits arachidonic acid-induced breast cancer cell migration." (PMID 31235786, 2019). "Pharmacological activation of TRPV4 in a breast cancer cell line causes downregulation of adhesion molecules like E-cadherin and β-catenin." (PMID 29772843, 2018). "The data below shows that TRPV4 is not only associated with more aggressive subtypes of breast cancer (basal subtype in particular) but also with poorer DMSF in the breast cancer patients with basal subtype." (PMID 28530703, 2017). "In accord with the loss of function studies in 4T07 murine breast cancer cells, gain-of-function studies by overexpression of TRPV4 in MB468 showed enhanced cell blebability." (PMID 27291497, 2016). "Here, we show that TRPV4 protein and transcript is overexpressed in an experimental model of breast cancer metastasis and its overexpression is associated with the acquisition of extravasation traits by breast cancer cells." (PMID 27291497, 2016). "Gain and loss of function studies in murine and human breast cancer cells supported a role of TRPV4 in metastasis." (PMID 27291497, 2016). "Additionally, TRPV4 high expression is linked to increased cell migration in endothelial cells, pulmonary smooth muscle cells, breast cancer cells, glioblastoma." (PMID 33994356, 2021). "This context-dependent behavior parallels the reported function of other mechanosensitive proteins, such as TRPV4, which promotes breast cancer metastasis but inhibits glioma progression." (PMID 40977743, 2025). "In basal breast cancer TRPV4 is overexpressed, and MDA-MB-468 breast cancer cells which expresses high levels of TRPV4 induce death by both necrosis and apoptosis in response to activation of TRPV4 by GSK1016790A." (PMID 40078961, 2025). "While the role of TRPV4 in breast cancer progression has been assessed by various studies, its role in the homeostasis of normal mammary epithelium has gained less focus." (PMID 38514727, 2024). "TRPV4 expression seems to be highest in the basal-like subtype of breast carcinoma and its levels are also prominent in the metastatic lesions of invasive ductal carcinomas, correlating with tumor grade and size." (PMID 38514727, 2024). "In breast cancer cells, TRPV4 activation has significant implications on the EMT process through changes in the actin cytoskeleton and expression of EMT markers." (PMID 39517820, 2024).
breast carcinoma (continued). "The upregulation of TRPV4 has been identified in breast cancer cell lines with the potential to metastasize, and its expression appears to increase with tumor grade and size, and to correlate with poor survival." (PMID 37892239, 2023). "In breast cancer-derived endothelial cells, TRPV4 co-localizes with actin, regulates filopodia and lamellipodia changes, and improves cell motility." (PMID 37369706, 2023). "TRPV4 knockdown in breast cancer reduces the cellular blistering motility and flexibility by regulating ERM phosphorylation, contributing to the processes of tumor extravasation and transcellular migration." (PMID 37369706, 2023). "Many types of cancer, including liver cancer, breast cancer, esophageal squamous cell carcinoma, gastric cancer cells, and colon cancer, maintain high expression and activated characteristics of TRPV4." (PMID 37369706, 2023). "In breast cancer, TRPV4 activation decreases the viability of two basal breast cancer cell lines with endogenous overexpression of TRPV4." (PMID 37762011, 2023). "In contrast, TRPV4 was found to be indispensable for breast cancer cell invasion and migration, as its overexpression promoted vesicle formation and actin reorganization in breast cancer tumor cells." (PMID 37762011, 2023). "Preclinical investigations have shown that TRPV4 agonist GSK1016790A inhibits breast cancer cell growth by calcium overload-induced apoptosis." (PMID 37369706, 2023). "TRPV4 was elevated in colon cancer, basal-like breast cancer and tumor-derived endothelial cells, but was downregulated in keratinocytes in non-melanoma skin cancer." (PMID 36619170, 2022). "TRPV4 overexpression is correlated with significantly poorer overall survival and disease-free survival in breast cancer patients." (PMID 36158191, 2022). "Breast cancer cells pre-exposed to elevated viscosity acquire TRPV4-dependent mechanical memory through transcriptional control of the Hippo pathway, leading to increased migration in zebrafish, extravasation in chick embryos and lung colonization in mice." (PMID 36323783, 2022). "Extracellular fluid viscosity promotes breast cancer cell migration by TRPV4-dependent Hippo pathway." (PMID 36619170, 2022). "On the other hand, activation of TRPV4 enhanced epithelial to mesenchymal transition (EMT) in breast cancer cells, which is critical for metastasis and therapeutic resistance." (PMID 36619170, 2022). "Another study showed that transient receptor potential cation channel subfamily V member 4 (TRPV4) increased the migration of breast cancer cells via remodeling of the actin cytoskeleton through the Ca2+-dependent activation of AKT." (PMID 33802790, 2021). "In line with our results, WH and colleagues suggested that TRPV4 dysfunction decreased aggression in breast cancer cells." (PMID 34814869, 2021). "TRPV4 has been observed to be upregulated in metastatic breast cancer cell lines 4T07, 4T1, and MDA-MB-468, compared to primary tumors that were unable to undergo extravasation." (PMID 34831037, 2021). "A significant upregulation of TRPV4 has been detected in breast cancer cell lines with the potential to metastasize and its expression seems to increase with tumor grade and size, subsequently correlating with poor survival." (PMID 34356643, 2021). "Recent studies show that pharmacological activation of TRPV4 resulted in reduced tumor growth in breast cancer through oncosis and apoptosis." (PMID 34389740, 2021). "High TRPV4 levels thus favor breast cancer metastasis by regulating cell-cell contacts, actin-dependent cell compliance, cell migration and extravasation through the AKT-E-cadherin signaling." (PMID 34356643, 2021). "For example, overexpression of TRPV4 promotes epithelial to mesenchymal transition in breast cancer cells." (PMID 34262942, 2021).
breast carcinoma (continued). "As reviewed above, TRPV4 can possibly potentiate invasion of breast cancer cells through Ca2+-dependent activation of AKT that leads to changes in actin dynamics and downregulation of junctional E-cadherin." (PMID 34356643, 2021). "In line with this, breast cancer models have shown that TRPV4 over-expression impacts cancer cell migration by leading to the higher activity of ROCK-regulated cofilin that promotes actin filament depolymerization." (PMID 34356643, 2021). "Silencing or inhibition of TRPV4 by chemical compounds also clearly suppresses the migratory features of TRPV4-expressing 4T07 breast cancer cells, further confirming the role of TRPV4 in cancer metastasis." (PMID 34356643, 2021). "TRPV4 plays an oncogenic role in breast cancer, endometrial cancer, gastric cancer, oral squamous cell carcinoma, and COAD and a suppressor gene role in glioma." (PMID 34262942, 2021). "It was observed that WT TRPV4 overexpression led to increased breast cancer cell invasion, through regulation of cell stiffness, blebbing, and actin cortex; the effects were mediated by Ca2+-dependent activation of Akt and E-cadherin down-regulation." (PMID 32186440, 2020). "This would be in excellent agreement with recent published works on cytoskeleton/adhesion regulation by TRPV4 mediating breast cancer metastasis." (PMID 32186440, 2020). "In breast cancer, TRPV4 levels are elevated in basal-like breast cancers compared with other molecular breast cancer subtypes." (PMID 33322037, 2020). "Our detailed assessment began with defining the contribution of TRPV4 to the sustained phase of Ca2+ influx induced by a variety of activators in EMT-inducible MDA-MB-468 breast cancer cells." (PMID 33322037, 2020). "TRPV4 was recently reported to be involved in breast cancer metastasis, through its action of softening the cell cortex by regulation of cytoskeleton/cortex proteins (actin/ERM/cadherin), by Ca2+-dependent activation of AKT and E-cadherin downregulation." (PMID 32186440, 2020). "TRPV4 is downregulated in prostate, skin, and breast cancers, while TRPV6 is boosted in various tumors, including prostate and breast cancers." (PMID 33171939, 2020). "In these studies, we sought to explore the relationship between TRPV4 gene expression levels and breast cancer molecular subtypes, prognosis, and EMT." (PMID 33322037, 2020). "Silencing of TRPV4 reduces migration and invasiveness in mouse 4T07 mammary cancer cells in vitro and suppresses the metastasis of 4T1 breast cancer cells in vivo." (PMID 33322037, 2020). "The role of TRPV4 in breast cancers is much complicated, making it difficult to be a potential drug target at present." (PMID 32211326, 2020). "Previous studies of the role of TRPV4 in breast cancer development have demonstrated that overexpression of TRPV4 can lead to a decrease in E-cadherin expression, driving EMT in this cancer type." (PMID 32228863, 2020). "Accordingly, TRPV4 knockdown reduced migration, invasion and transendothelial migration in breast cancer cells." (PMID 33132914, 2020). "Assessment of the consequences of GSK1016790A treatment in another model of EMT in breast cancer cells supported the ability of TRPV4 activation to induce EMT marker expression." (PMID 33322037, 2020). "Knockdown of TRPV4 decreases breast cancer cell invasiveness in vitro and lung metastasis in vivo, and further investigation revealed that TRPV4 promotes breast cancer metastasis via Ca2+-dependent activation of AKT and downregulation of E-cadherin expression." (PMID 32825277, 2020). "Pronounced overexpression of TRPV4 in some breast cancers has been exploited in vitro and in vivo through pharmacological activation and subsequent promotion of cell death and suppression of tumor growth." (PMID 33322037, 2020).